Y_RNA (Y RNA )
Gene: Miscellaneous RNA gene on chromosome 7 (146,311,720 to 146,311,822, forward strand). Ensembl gene ENSG00000274118.
Homologues: Orthologues: chimpanzee Y_RNA (99% identical). Paralogues in human: Y_RNA (84% identical), Y_RNA (81% identical), RNY3 (80% identical), Y_RNA (80% identical), RNY3P1 (79% identical), Y_RNA (79% identical), Y_RNA (78% identical), Y_RNA (77% identical), Y_RNA (76% identical), Y_RNA (75% identical), RNY3P11 (74% identical), RNY3P14 (74% identical), and 91 more.